SMG8 (SMG8 nonsense mediated mRNA decay factor)
Description:
Involved in nonsense-mediated decay (NMD) of mRNAs containing premature stop codons. Is recruited by release factors to stalled ribosomes together with SMG1 and SMG9 (forming the SMG1C protein kinase complex) and, in the SMG1C complex, is required to mediate the recruitment of SMG1 to the ribosome:SURF complex and to suppress SMG1 kinase activity until the ribosome:SURF complex locates the exon junction complex (EJC). Acts as a regulator of kinase activity.
Synonyms: C17orf71; FLJ10587; FLJ23205; ALKUS
Tractability: Small molecule: a structure with a bound ligand is known. PROTAC: ubiquitination databases record sites on it; its protein half-life has been measured.
Gene: Protein-coding gene on chromosome 17 (59,209,400 to 59,215,248, forward strand). Ensembl gene ENSG00000167447.
Subcellular location (Human Protein Atlas): Nucleoplasm; Cytosol; Primary cilium; Primary cilium tip; Vesicles
Pathways (Reactome):
Metabolism of RNA: Nonsense Mediated Decay (NMD) enhanced by the Exon Junction Complex (EJC)
Gene Ontology:
Molecular function: protein binding
Biological process: nuclear-transcribed mRNA catabolic process, nonsense-mediated decay; regulation of protein kinase activity; regulation of nuclear-transcribed mRNA catabolic process, nonsense-mediated decay
Cellular component: serine/threonine protein kinase complex; cytosol
Genetic constraint (gnomAD): Loss-of-function variants: 45 observed, 79.43 expected, observed/expected ratio (o/e) 0.57, 90% interval 0.44 to 0.73. The upper end of that interval is the gene's LOEUF score, 0.73, which puts it in group 2 of 6, group 1 being the genes least tolerant of losing a copy. Missense variants: 887 observed, 1,153.5 expected, observed/expected ratio (o/e) 0.77, 90% interval 0.73 to 0.81. Synonymous variants: 372 observed, 427.54 expected, observed/expected ratio (o/e) 0.87, 90% interval 0.8 to 0.95.
Gene-disease validity (ClinGen):
ClinGen rates the evidence that SMG8 causes each of these diseases.
Alzahrani-Kuwahara syndrome (autosomal recessive): Definitive.
Homologues: Orthologues: chimpanzee SMG8 (99% identical), macaque SMG8 (99% identical), dog SMG8 (98% identical), rabbit SMG8 (97% identical), guinea pig SMG8 (96% identical), mouse Smg8 (96% identical), rat Smg8 (95% identical), tropical clawed frog smg8 (71% identical), zebrafish smg8 (64% identical), Drosophila melanogaster CG6729 (25% identical), Caenorhabditis elegans smg-8 (21% identical).
Diseases named in the same sentence as SMG8 in open-access papers:
SMG8 is named in the same sentence as 8 diseases in open-access papers, as found by Europe PMC text mining. Sharing a sentence is not in itself a finding about the gene and the disease. The quoted sentences say what the papers report.
chronic myelogenous leukemia (1 paper, 2022). "ATRi resistance within the context of SMG8 or SMG9 deficiency was not unique to the YCC6 cells; SMG8 or SMG9 mutant HAP1 cells (chronic myelogenous leukemia cells with homozygous premature truncating mutations and loss of WT protein) were also resistant to ATRi." (PMID 36273494, 2022).
gastric cancer (1 paper, 2022). A primary or metastatic malignant neoplasm involving the stomach. "Here, we used a positive selection genome-wide CRISPR-Cas9 screen to identify candidate regulators of ATRi resistance in gastric cancer, including loss-of-function mutations in either SMG8 or SMG9 that appeared to cause ATRi resistance by a SMG1-mediated mechanism." (PMID 36273494, 2022).
cancer (3 papers, 2024 to 2025). A tumor composed of atypical neoplastic, often pleomorphic cells that invade other tissues. "In particular, the cancer-derived mutations within SMG1 located at 248–910 and 2200–2400 amino acids were evaluated in terms of the change in affinity or stability in the presence of SMG8/SMG9 and UPF1, respectively." (PMID 41189592, 2025). "In addition, the effect of cancer-derived mutations in SMG1 (located within 248 aa–910 aa and 2,200 aa–2,400 aa) was characterized, and their effects on the binding affinity and stability in the presence of SMG8, SMG9, and UPF1 were predicted." (PMID 41189592, 2025).
neurodevelopmental disorder (2 papers, 2022 to 2024). A behavioral and cognitive disorder with onset during the developmental period that involves impaired or aberrant development of intellectual, motor, or social functions. "For instance, loss-of-function mutations in UPF2, UPF3B, SMG8 and SMG9 genes, and CNVs targeting UPF2, UPF3A, SMG6, EIF4A3, RNPS1 and RBM8A genes, have been implicated in a variety of neurodevelopmental disorders, including DD, ID, ADHD and TAR syndrome." (PMID 35327467, 2022).
tumor (1 paper, 2020). "In the first pathway, in early-stage CRC, the upregulated CASC2 transmits the signal to HINFP, which is modified by ubiquitination to inhibit tumor growth, and transmits the signal to TF TCF3 through SMG8." (PMID 32211020, 2020).
SMG8 also shares sentences with these, for which no sentence is quoted: Ullrich congenital muscular dystrophy (2 papers); Alzahrani-Kuwahara syndrome (1); colorectal tumor (1).